MTOR (mechanistic target of rapamycin kinase)
Diseases named in the same sentence as MTOR in open-access papers (continued):
Sharing a sentence is not in itself a finding about the gene and the disease.
cancer (continued). "However, the fast development of large numbers of resistant clones under AKT/mTOR therapy observed in vitro and in the orthotopic xenotransplantation mouse model in vivo strongly suggests that this therapy alone will not be sufficient to eliminate EpCAM+ or CD90+ cancer stem cells from HCC patients." (PMID 35454789, 2022). "However, little or no ATF4 activation or mTOR suppression was detected upon OXPHOS inhibition in resistant cancer cells (CFPAC‐1, 786‐O, and SF126) under the same treatments, suggesting very limited induction of cellular stress responses in these cancer cells upon OXPHOS inhibition." (PMID 36382559, 2022). "Autophagy inducers, such as mTOR inhibitors in cases of GC-disseminated-type or AMPK homeostatic pathway activators such as the antibiotic substance Tigecycline, could be used in cases of chemoresistant GC, in which other anti-cancer treatments failed to reduce the cancer progression." (PMID 34947835, 2021). "Cancerous and noncancerous tissues from 12 patients with HSCC were examined for the expression of mTOR by using real-time quantitative reverse transcriptase-polymerase chain reaction (qRT-PCR) in order to elucidate whether the expression levels of mTOR were altered in cancerous tissues." (PMID 29760955, 2018). "Therefore, our results suggest that Reishi’s anti-cancer effect is not exclusively through eIF4G downregulation, but likely occurs through an inhibitory combination of signaling pathways that include PI3K and mTOR pathways and on levels/activity of eIF4F complex proteins." (PMID 23468988, 2013).
tumor (9,050 papers, 2004 to 2026). "Collectively, this work establishes a causal link between tumour-resident E. faecalis and hepatocarcinogenesis, revealing EF-Obg as a cross-kingdom activator of mTOR and providing a rationale for microbiota-guided personalised therapy in HCC." (PMID 42310938, 2026). "Mechanistically, BCR loss impaired mTOR-dependent anabolic control, reducing protein synthesis, while diminished Cyclin D3 abundance sensitized tumor cells to pharmacological CDK4/6 blockade." (PMID 41668618, 2026). "Aberrant activation of the PI3K/AKT/mTOR pathway promotes tumor cell growth and survival, and is also strongly associated with the resistance to chemotherapy and endocrine therapy." (PMID 41510186, 2026). "Consequentially, the upregulation of mTOR and its downstream components seem to be associated with a more aggressive tumor behavior, with a higher tendency for distant metastases and a shorter overall survival." (PMID 40002868, 2025). "PI3K/AKT/ mTOR signaling pathway also plays a role in regulating M1/M2 polarization of macrophages, similar to the tumor-associated macrophage (TAM) switch between immune stimulation and immune suppression." (PMID 40179068, 2025). "SSAs exhibit antiangiogenic properties by downregulating VEGF, while mTOR inhibitors disrupt tumor-associated stromal support and nutrient supply." (PMID 39996718, 2025). "Emerging evidence across multiple tumor models has established an inverse regulatory relationship between PI3K/Akt/mTOR activation and ferroptosis susceptibility." (PMID 40993737, 2025). "Phosphoinositide 3-kinase/protein kinase B/mechanistic target of rapamycin (PI3K/Akt/mTOR) inhibitors combined with OVs offers a promising strategy to enhance tumor susceptibility to oncolysis and modulate TME for better outcomes." (PMID 40927720, 2025). "Stimulation of both oncogene-induced RAS-activated PI3K together with the amplification of mutation on its major effector, AKT and mTOR drives the malignant resistance and tumor progression." (PMID 39860214, 2025). "For instance, N2-type TANs fuel tumor growth via ROS, which activates pro-survival pathways (NF-κB, PI3K/Akt/mTOR) in cancer cells, promotes angiogenesis, suppresses anti-tumor immunity (T cells, NK cells), and can cause DNA damage." (PMID 41459159, 2025). "The prevalent enrichment of the DNA replication and PI3K/MTOR signaling pathways across both risk groups is particularly notable, as these pathways are critically involved in tumor cell proliferation, survival, and resistance to treatment." (PMID 41019288, 2025). "They observed that IST treatment resulted in reduced melanoma tumor growth and inhibited the AKT/mTOR pathway, which is associated with tumor progression." (PMID 40003608, 2025). "These tumor suppressor genes encode the proteins tuberin and hamartin, respectively, which together comprise an inhibitory heterodimer to the mammalian target of rapamycin (mTOR) cell growth and proliferation pathway." (PMID 40636662, 2025). "Gemcitabine activates the AMPK/mTOR pathway, raising the expression of AMPK and reducing that of mTOR, leading to cell autophagy, which causes tumour cells to stop growing and undergo apoptosis." (PMID 41151762, 2025). "The PI3K/Akt/mTOR pathway is a major tumor signaling pathway, implicated in numerous oncogenic processes, including cell proliferation and migration and inhibition of apoptosis." (PMID 40647529, 2025). "Aberrant activation of the PI3K/AKT/mTOR pathway acts as a tumor trigger in HER2 + BC due to mutations in PI3KCA or PTEN." (PMID 40668275, 2025). "Spermine was shown to induce tumor-associated macrophages to polarize toward the M2 phenotype primarily through the activation of the PI3K-Akt-mTOR-S6K signaling pathway, which subsequently diminished the anti-tumor activity of CD8+ T cells." (PMID 41440201, 2025). "The result also aligns well with the observed sphingolipid up-regulation of mTOR due to RAC1A159V mutation in the tumor cells." (PMID 41160695, 2025).
tumor (continued). "Given its role in cell proliferation, growth and morphology, mutations affecting the mTOR pathway are also likely to contribute to the tumor-driven circuit remodeling that has been observed in recent studies." (PMID 41074169, 2025). "The PI3K/AKT/mTOR pathway, associated with MT‐mediated resistance, can be targeted with everolimus to reduce mesenchymal markers and delay tumor recurrence in HNSCC, NSCLC, and renal cell cancer." (PMID 40895189, 2025). "miR-100c is highly expressed in tumor-associated macrophages (TAMs) and supports the maintenance of their phenotype by regulating the mTOR signaling pathway." (PMID 40761244, 2025). "In TNBC the LKB1 deficiency promotes tumor growth and metastasis by enhancing glycolysis and activating the mTOR- HIF-1α axis, which supports TNBC cells survival and proliferation under metabolic stress." (PMID 41436543, 2025). "A study on breast cancer demonstrated that reduced B7-H3 expression leads to a decrease in glycolytic capacity, rendering tumor cells more susceptible to AKT/mTOR inhibitors." (PMID 41463642, 2025). "Our study further delineates a functional link where KDM5B downregulates PLK2 expression by reducing the H3K4me3 levels at the promoter, thereby activating the PI3K/AKT/mTOR pathway to promote tumor progression in EBV-associated epithelial tumors." (PMID 40059116, 2025). "Detected across consensus, local, and dependence SHAP interpretations, this gene encodes a glutamine transporter critical for tumor metabolism and mTOR pathway activation." (PMID 40941703, 2025). "These mutations result in constitutive mTOR pathway activation, promoting tumor cell growth and proliferation, and providing a rational target for mTOR inhibitor therapy." (PMID 41463261, 2025). "The activation of the PI3K/Akt/mTOR pathway has been found to be associated with increased immunosuppressive functions of MDSCs in different tumor models." (PMID 40725182, 2025). "Studies have shown that activation of the PI3K/Akt/mTOR pathway is a key mechanism underlying radiation resistance in tumor cells across multiple radiotherapy models." (PMID 41178971, 2025). "Dose-dependent reduction in proliferation and viability of PaCa-2 and Huh7 tumor cell lines via lowering of mRNA METTL3 level.Its mechanism is associated with PI3K/Akt/mTOR, Wnt/b-catenin, and MAPK/ERK1/2 pathways." (PMID 41157107, 2025). "Current treatments primarily rely on mTOR inhibitors, such as rapamycin, which reduce seizure frequency and tumor size but fail to address underlying genetic causes." (PMID 40358185, 2025). "Overactivation of the mTOR pathway promotes cell division and growth, which is directly linked to tumor development and progression." (PMID 40303296, 2025). "Tumor sequencing data derived from patients revealed an association of aberrant mTOR activation with neratinib resistance." (PMID 39908697, 2025). "The PI3K/AKT/mTOR pathway is frequently hyperactivated in BC, which is closely associated with tumor cell proliferation, metabolism, and resistance." (PMID 41359105, 2025). "The overactivation of the PI3K/Akt/mTOR signaling axis is closely associated with tumor cell proliferation, growth, death, and other processes." (PMID 39871325, 2025). "Osteopontin, another key TME component, is linked to poor prognosis and promotes tumor growth via the Akt/mTOR/p70S6K signaling pathway." (PMID 41353504, 2025). "Key biomarkers such as GLUT-1, FASN, and enzymes involved in ferroptosis, cholesterol biosynthesis, and amino acid catabolism demonstrate strong associations with tumor aggressiveness, hypoxia, and mTOR signaling." (PMID 41458541, 2025). "Loss of GNMT tumor suppressor function results in unchecked activation of the mTOR signaling pathway, promoting HCC cell proliferation, motility, and tumor invasion." (PMID 41465470, 2025).
tumor (continued). "The loss of STK11 function is the well-known cause for the activation of the AMPK/mTOR pathway, which, paradoxically, enables tumor cells to survive and become resistant to metabolic stress." (PMID 41155343, 2025). "The AMPECT trial evaluated the significant anti-tumor activity of nab-sirolimus in patients with advanced or metastatic malignant PEComa carrying mutations in the TSC1/TSC2 genes or activation of the mTOR pathway." (PMID 40989692, 2025). "PTEN loss, primarily through PI3K/AKT/mTOR pathway dysregulation, facilitates tumour progression by promoting cell survival, proliferation, and resistance to apoptosis." (PMID 40940958, 2025). "Another study revealed that PGAM1 is a critical regulator of mTOR-mediated tumour growth and is associated with aggressive NSCLC phenotypes." (PMID 41154605, 2025). "Aberrant mTOR pathway activation, induced by loss of tumor suppressors or oncogenic stimulation, significantly promotes tumor growth, angiogenesis, and metastasis." (PMID 41219936, 2025). "Key pathways implicated in both GAE and tumor biology include the IDH and mTOR signaling and a range of tumor related somatic mutations." (PMID 41074169, 2025). "Some cases have shown additional genetic alterations, including activating mutations in PIK3CA and MTOR, suggesting potential molecular pathways involved in tumor growth." (PMID 41246635, 2025). "In preclinical studies, the pan-PI3K inhibitor dactolisib, a dual ATP-competitive pan-PI3K and mTOR inhibitor, in combination with enzalutamide has been shown to effectively induce tumor regression in the MYC-overexpressing and PTEN-deficient GEM model." (PMID 40427108, 2025). "Abnormal activation of the PI3K/AKT/mTOR signaling pathway due to mutations in PIK3CA can promote tumor growth, angiogenesis, and resistance to apoptosis." (PMID 39744583, 2025). "mTOR inhibition has been associated with reduced tumor development and enhanced response to therapy, suggesting a role in SASP modulation for effective treatment." (PMID 41463272, 2025). "Beyond its potent antiangiogenic effects, Apatinib has been shown to modulate tumor-associated signaling pathways such as PI3K/AKT/mTOR and ROS/Nrf2/p62, thereby promoting tumor cell apoptosis and enhancing sensitivity to chemotherapeutic agents." (PMID 41394216, 2025). "mTOR inhibitors can reduce tumor size and decrease the risk of secondary rupture bleeding in patients with high-risk TSC-associated RAML." (PMID 41194857, 2025). "Crosstalk between insulin and insulin-like growth factor (IGF) signaling and oncogenic pathways such as PI3K/AKT/mTOR provides a mechanistic basis for these associations, highlighting the interplay between metabolism and tumor biology." (PMID 41157306, 2025). "Previous studies have shown that PI3K/AKT/mTOR pathway activation is linked to tumor progression, therapy resistance, and poor prognosis, particularly in tumors with high metabolic demand." (PMID 40282485, 2025). "Under stressed conditions (CUMS), MO inhibited mTOR while increasing miR- 217, aligning with its isothiocyanate-mediated mTOR suppression, which has been linked to anti-tumor activity with minimal toxicity." (PMID 40266546, 2025). "By inhibiting mTOR, Rapamycin can effectively block tumor cell dependence on glycolysis in the high-risk group, inducing metabolic inhibition as well as cell death." (PMID 40115255, 2025). "Metformin-mediated mTOR inhibition suppressed tumorigenesis-associated glycolysis and promoted tumor cell apoptosis, confirming a critical role of metformin in combinational cancer treatments." (PMID 39776799, 2025). "PIK3CA mutations lead to the sustained activation of the PI3K/AKT/mTOR signaling pathway, thereby promoting tumor cell proliferation, survival, and invasion." (PMID 41280894, 2025).
tumor (continued). "Key genetic alterations include mutations in BRAF, NF1, and PTEN, elevated mTOR expression, and specific miRNA profiles, which influence tumour progression and response to therapy." (PMID 40831998, 2025). "The phosphoinositide 3-kinase (PI3K)/protein kinase B (AKT) pathway, loss of Phosphatase and tensin homolog (PTEN), and Mammalian Target of Rapamycin (mTOR) signaling also work in concert with NRF2 to promote tumor growth." (PMID 40563292, 2025). "An immunohistochemical study of 30 patients demonstrated overexpression of phosphorylated Akt and mTOR in tumor tissues compared with normal bile ducts, findings associated with poor prognosis." (PMID 41155242, 2025). "For instance, chronic RAS signaling can affect cell growth via mTOR, which is associated with the anti-apoptotic properties of tumor cells." (PMID 41301459, 2025). "Microarray analysis has shown that the extent of PTEN loss and the upregulation of p-mTOR and p-Akt are significantly correlated with vascular invasion, intrahepatic metastasis, and tumor grading." (PMID 40699663, 2025). "In PanNETs, overactivity of the PI3K-Akt-mTOR pathway is thought to cause tumor initiation and progression." (PMID 41375037, 2025). "Prolonged mTOR inhibition also induces an adaptive increase in glutamine catabolism, allowing tumor cells to avoid the loss of glycolysis and thus mediate resistance to mTOR inhibition." (PMID 40018041, 2025). "Aberrant mTOR activation promotes an immunosuppressive environment by changing T-cell function and enabling tumor-associated macrophage polarisation, resulting in tumor progression and resistance to treatment." (PMID 40872585, 2025). "Mutations in the PI3K pathway activate downstream AKT and mTOR signaling pathways, promoting cell proliferation, survival, and migration, consequently driving tumor progression and metastasis." (PMID 40328748, 2025). "Loss of CMTM4 significantly reduced pAKT/mTOR signaling, which is consistent with our findings in murine tumor cell lines." (PMID 39948411, 2025). "The first cohort study indicated that tumor samples with PIK3 CA mutations were associated with high PI3 K/AKT/mTOR signaling and stemness scores." (PMID 40676293, 2025). "We next examined the functional consequences of MITF loss on mTOR inhibition-induced autophagy and on extracellular vesicle (EV) content and secretion, given their known interplay in tumor progression." (PMID 41168571, 2025). "The most prevalent off‐target alteration after 6 months of first‐line alectinib treatment was the NF2 mutation, a tumor suppressor in the PI3K/mTOR/Akt pathway that encodes for the merlin protein." (PMID 40168046, 2025). "MEK inhibitors have been studied as single medicines or in conjunction with PI3K/mTOR inhibitors for tumours with NRAS mutations, although data regarding their application in advanced CoM with NRAS mutation is lacking." (PMID 40831998, 2025). "Mutations in these genes disrupt their function as tumor suppressors, leading to abnormal cell growth and development via dysregulation of the mTOR pathway." (PMID 41462762, 2025). "In summary, our findings showed a loss of CMTM4 inhibited tumor growth in vivo, and reduced Akt/mTOR signaling and NF-κB activation, which are dependent on the CMTM4 TRAF6 domain." (PMID 39948411, 2025).